PTH (parathyroid hormone)
Diseases named in the same sentence as PTH in open-access papers (continued):
Sharing a sentence is not in itself a finding about the gene and the disease.
preeclampsia (6 papers, 2014 to 2025). Preeclampsia is a hypertensive disorder of pregnancy that is characterized by new-onset hypertension with proteinuria presenting after 20 weeks of gestation, and depending on mild or severe forms may initially present with severe headache, visual disturbances, and hyperreflexia. "We found evidence for ethnic differences in associations between maternal 25(OH)D and PTH with gestational hypertension." (PMID 30718630, 2019). "We used multinomial or logistic regression to explore the association between vitamin D, PTH and calcium with gestational hypertension (GH), pre-eclampsia (PE), caesarean section (CS), preterm birth (PTB) and small for gestational age (SGA)." (PMID 30718630, 2019). "Additionally, several studies reported an increased risk of preeclampsia for only certain thrombophilia markers, the PTH variant, the FVL variant, the homozygotes MTHFR variant, and anti-phospholipid antibodies." (PMID 36420283, 2022). "This would be consistent with higher PTH levels in women affected by preeclampsia, indicating a chronic impairment of renal function." (PMID 25148115, 2014).
renal fibrosis (6 papers, 2017 to 2025). A final common manifestation of a wide variety of chronic kidney diseases characterized by glomerulosclerosis and tubulointerstitial fibrosis. "Taken as a whole, our study indicated that the overexpression of TβRI enhanced renal dysfunction, as shown by increasing serum urea nitrogen and renal fibrosis, which contributed to the dysregulation of calcium and PTH levels during CKD." (PMID 40141345, 2025). "Part of these mechanisms are shared with renal fibrosis, where in addition, PTH enhances connective tissue growth factor (CTGF) expression in proximal tubular cells." (PMID 33401711, 2021). "Recently, many doctors have come to the conclusion that PTH expedites the progression of renal fibrosis by stimulating renal tubular epithelial cells to secrete fibronectin and TGF-β1." (PMID 28741985, 2017). "Fasudil can restrain EMT induced by PTH; this conclusion provides experimental data for the application of fasudil in the clinical prevention and treatment of renal fibrosis." (PMID 28741985, 2017). "Furthermore, PTH promotes endothelial-to-mesenchymal transition in the glomeruli, and in this way accelerates the progression of renal fibrosis." (PMID 38280162, 2024).
small cell lung carcinoma (6 papers, 2013 to 2025). Small cell lung cancer (SCLC) is a highly aggressive malignant neoplasm, accounting for 10-15% of lung cancer cases, characterized byrapid growth, and early metastasis. "In contrast, it is rare in small-cell lung carcinoma (SCLC), where parathyroid hormone levels remain mostly within the normal range despite elevated calcium." (PMID 40837924, 2025). "GSCC can present with paraneoplastic syndromes, as occurs with small-cell lung cancer (SCLC), and secrete ectopic hormones, such as parathyroid hormone, antidiuretic hormone, calcitonin, or serotonin." (PMID 23662228, 2013).
thyrotoxicosis (6 papers, 2012 to 2024). A hypermetabolic syndrome caused by the elevation of thyroid hormone levels in the serum. "Upon treatment of the thyrotoxicosis, serum calcium fell transiently, and PTH and 1,25OH2D3 increased." (PMID 36166168, 2023). "We demonstrated that restoration of an euthyroid state after treatment of thyrotoxicosis is associated with a significant decrease of sclerostin, osteocalcin, and CTX serum concentrations coinciding with an increase of PTH concentrations." (PMID 26366174, 2015). "This is because a fall of PTH concentration was reported in subjects with thyrotoxicosis, followed by an increase during anti-thyroid treatment." (PMID 23146624, 2012).
asthma (5 papers, 2013 to 2025). "Further studies are necessary, including strategies looking at markers of vitamin D pathway such as PTH and 1,25(OH)2D to better understand the impact of genetic variants on the metabolism of vitamin D, including as interaction analysis to understand its role in asthma and atopy." (PMID 32834827, 2020). "The mean serum Ca and PTH levels were significantly higher in healthy controls compared to asthma patients (p = 0.04, p = 0.004, respectively)." (PMID 24330502, 2013). "Data were obtained from medical records and structured questionnaires, including socio-demographic characteristics, asthma control status, exacerbation frequency, hospitalization history, and biochemical assays (serum vitamin D, calcium, phosphate, parathyroid hormone)." (PMID 41477232, 2025).
autoimmune thyroid disease (5 papers, 2013 to 2025). Inflammatory disease of the thyroid gland due to autoimmune responses leading to lymphocytic infiltration of the gland. "Kegg pathway analysis showed that transcripts associated with ‘autoimmune thyroid disease’ and ‘parathyroid hormone synthesis, secretion and action’ were differentially expressed across the transition." (PMID 34100896, 2021). "These include parathyroid hormone synthesis, secretion of thyroid hormone, and action of thyroid hormone signaling pathways and autoimmune thyroid diseases." (PMID 35720300, 2022).
colorectal cancer (5 papers, 2013 to 2024). A primary or metastatic malignant neoplasm that affects the colon or rectum. "However, vaccinia altered signaling pathways are mainly enriched in parathyroid hormone synthesis, secretion and action, ErbB signaling pathway, colorectal cancer, Neomycin, kanamycin and gentamicin biosynthesis, carbohydrate digestion and absorption, and other types of O-glycan biosynthesis." (PMID 38737277, 2024).
deficiencies (5 papers, 2013 to 2024). "Assessment of the prevalence of nutritional deficiencies in the present study in various follow-up visits over a ten-year period showed that PTH varied significantly." (PMID 30539982, 2018). "Higher PTH levels following RYBP, compared to SG, may imply we are undertreating patients who are inherently subjected to a greater degree of malabsorption and underlying nutritional deficiencies." (PMID 34563195, 2021). "The bone profile of patients with 25(OH) D deficiencies is shown in Table-I, while Table-II shows the correlation between the levels of 25(OH) D and bone profile (calcium, magnesium, phosphate, alkaline phosthatase and PTH) with the presence or absence of neurological presentations in the subjects." (PMID 24353618, 2013).
DiGeorge syndrome (5 papers, 2007 to 2026). "Children with DiGeorge syndrome had even lower PTH levels (6.3 pg/mL) and preserved phosphate." (PMID 41704483, 2026).
disc degeneration (5 papers, 2016 to 2024). "Intermittent injection of PTH (iPTH) effectively attenuates disc degeneration of aged mice by direct signaling through NP cells, specifically improving intervertebral disc height and volume by increasing levels of TGF-β activity, CCN2, and aggrecan." (PMID 30038820, 2018). "The present study was performed with female SD rats; the intervention included ovariectomy and oestrogen or PTH replacement, the degeneration time was set to 5 months after ovariectomy, and we studied the Wnt/β-catenin pathway changes during disc degeneration." (PMID 27279629, 2016). "β-catenin, c-myc and cyclin D1 mRNA expression in the OVX+E2 and OVX+PTH groups were higher than those in the OVX group, indicating that oestrogen and PTH could increase the Wnt/β-catenin pathway expression at the same time as when they relieve disc degeneration." (PMID 27279629, 2016). "Thus, PTH activates latent TGF-β by increasing αvβ6 expression in NP tissue, offering a potential therapeutic target for disc degeneration." (PMID 30038820, 2018). "Although parathyroid hormone 1–34 has substantial anabolic effects on bone mass and trabecular microarchitecture, nonsignificant effects have not yet been found on disc degeneration." (PMID 30201052, 2018).
endometrial cancer (5 papers, 2014 to 2023). Primary or metastatic malignant neoplasm involving the endometrium (mucous membrane that lines the endometrial cavity). "The pathology confirmed mismatch repair (MMR)-deficient endometrial carcinoma with PTH expression." (PMID 36798668, 2023).
escherichia coli infection (5 papers, 2022 to 2024). Infection with the organism Escherichia Coli. "The Q4-enriched proteins were involved in parathyroid hormone synthesis, secretion and action, legionellosis, pathogenic Escherichia coli infection, the NOD-like receptor signaling pathway, longevity regulating pathway, gap junctions, tight junctions, and cholesterol metabolism." (PMID 37701139, 2023).
fibrosis (5 papers, 2012 to 2024). the formation of excess fibrous connective tissue in an organ or tissue in a reparative or reactive process. "Beyond its role in bone turnover, elevated PTH, in the long run, mediates vascular and valvular calcification, cardiovascular fibrosis, and apoptosis through the transforming growth factor beta (TGF-β) signalling pathway." (PMID 39310569, 2024). "We studied the associations of calcium, phosphate, 25D, PTH, FGF23, Klotho and T50 with histological fibrosis." (PMID 28036331, 2016). "Cheng and colleagues have found that activation of the vascular smooth muscle parathyroid hormone receptor by PTH inhibits Wnt/β-catenin signaling, type I collagen protein accumulation, and aortic fibrosis and calcification in diabetic arteriosclerosis." (PMID 23304079, 2012).
growth failure (5 papers, 2019 to 2024). "PTH levels ≥100 pg/mL have been found associated with adynamic bone disease and growth failure in children on maintenance dialysis, indicating that PTH levels should be targeted in advanced CKD." (PMID 39062256, 2024). "PTH levels were correlated with height z-score, and growth failure was associated with worse nutritional status." (PMID 39094068, 2024). "Moreover, PTH levels were inversely correlated with the height/age z-score, and growth failure in these children was associated with worse nutritional status." (PMID 39094068, 2024). "What is the parathyroid hormone (PTH) level in children with growth failure and CKD above which you believe that rhGH treatment should not be started?" (PMID 33013690, 2020). "The association of CKD5 and dialysis with growth failure was not explained by variation of hemoglobin, serum bicarbonate, PTH, phosphorus or CRP (model 2)." (PMID 31334210, 2019). "A large disparity of opinions emerged between experts regarding serum PTH levels above which rhGH treatment should not be started in children with growth failure and CKD, with only 26% of them complying with the 2019 clinical practice recommendations." (PMID 33013690, 2020).
Hypermagnesemia (5 papers, 2019 to 2025). An abnormally increased magnesium concentration in the blood. "Hypermagnesemia can decrease PTH action through the adenylcyclase system and suppress PTH secretion by stimulating calcium-sensing receptors." (PMID 36382754, 2022).
idiopathic osteoporosis (5 papers, 2019 to 2025). "Clinical trials have demonstrated that increased parathyroid hormone levels lead to elevated osteocalcin levels and are effective in ameliorating idiopathic osteoporosis in men." (PMID 39872315, 2024). "We observed increased serum osteolectin levels after PTH treatment in premenopausal women with idiopathic osteoporosis, but whether similar effects would be observed in older postmenopausal women remains unclear." (PMID 34140410, 2021).
liver cirrhosis (5 papers, 2018 to 2025). "The metabolism of calcium and vitamin D is impaired in liver cirrhosis with the resultant parathyroid hormone (PTH) disturbance." (PMID 30225253, 2018).
malaria (5 papers, 2014 to 2024). Malaria is a serious and sometimes fatal disease caused by a parasite that commonly infects a certain type of mosquito which feeds on humans. "Exogeneous administration of hormones like DHEA, melatonin, PTH, Vitamin-D3, hepcidin, progesterone and erythropoietin have been reported to protect against malaria pathologies." (PMID 39492784, 2024). "In murine malaria, prolonged PTH treatment has been shown to prevent infection-induced proliferation of hematopoietic stem cells (HSCs), partially preserve osteoblasts, and lower global IFN-γ levels by reducing the number of IFN-γ-secreting T cells." (PMID 39492784, 2024). "Hormones such as DHEA, melatonin, PTH, Vitamin D3, hepcidin, progesterone, and erythropoietin protects against malaria." (PMID 39492784, 2024). "For example, coexpression of a protein disulfide isomerase increased the secretion of a malaria vaccine candidate (Pfs25) by 2- to 5-fold and increased the yield of a human parathyroid hormone (hPTH) from 127 mg/L to 349 mg/L." (PMID 30915359, 2019). "Since calcium is vital for the survival and replication of Plasmodium parasites, changes in PTH levels could affect calcium availability and influence malaria severity." (PMID 39492784, 2024).
metastasis (5 papers, 2018 to 2021). The spread or migration of cancer cells from one part of the body (where they first appeared) to another. "For liver and lung metastasis, radiofrequency ablation (alone or with arterial embolisation) has been reported as having a good chance to improve calcium and PTH levels." (PMID 34659402, 2021). "Multiple pulmonary nodules were detected by CT in one patient with repeated recurrences, suggesting pulmonary metastasis at 38 months (serum PTH: 75.6 pmol/L, calcium: 3.48 mmol/L)." (PMID 30290620, 2018).
migraine (5 papers, 2014 to 2025). "This continuing work is important in developing the headache field and exploring future treatment perspectives as shown in migraine and PTH studies." (PMID 37627930, 2023). "Materials and Methods: We retrospectively examined the patients’ levels of calcium, phosphorus, parathyroid hormone, alkaline phosphatase, and 25-OH vitamin D of 92 pediatric migraine patients." (PMID 31261815, 2019). "Migraine, MOH, and PTH show overlapping pathophysiology in regions associated with the cognitive-affective, sensory, and modulatory components of the “pain-matrix,” yet compared to migraine, patients with MOH and PTH have exacerbated changes within regions involved in multisensory integration." (PMID 32047470, 2019).
osteogenesis imperfecta (5 papers, 2013 to 2025). Osteogenesis imperfecta (OI) comprises a heterogeneous group of genetic disorders characterized by increased bone fragility, low bone mass, and susceptibility to bone fractures with variable severity. "Here, we present the baseline characteristics of participants in the Treatment of Osteogenesis Imperfecta with Parathyroid Hormone and Zoledronic Acid (TOPaZ) trial." (PMID 41206390, 2025). "The TOPAZ trial—Treatment of Osteogenesis Imperfecta with Parathyroid hormone and Zoledronic acid (NCT03735537) has recruited 350 patients across 29 sites in 5 countries." (PMID 38553634, 2024). "Tests for metabolic bone disease such as measuring levels of calcium, phosphorus, alkaline phosphatase (ALP), parathyroid hormone (PTH), vitamin D, copper, and ceruloplasmin should be done routinely, and testing for genetic disease, e.g., osteogenesis imperfecta, should be considered." (PMID 33308191, 2020).
Pancytopenia (5 papers, 2021 to 2026). An abnormal reduction in numbers of all blood cell types (red blood cells, white blood cells, and platelets). "Hemodialysis and erythropoietin were initiated and combined therapy with a phosphate binder and an active vitamin D agent achieved greater reduction of PTH levels, along with improvement of pancytopenia." (PMID 34046371, 2021). "Therefore, we recommend investigating refractory neutropenia or pancytopenia with bone profiles, including calcium, phosphate, and PTH levels." (PMID 41473619, 2025).
polycystic kidney disease (5 papers, 2012 to 2024). A usually autosomal dominant and less frequently autosomal recessive genetic disorder characterized by the presence of numerous cysts in the kidneys leading to end-stage renal failure. "In adenine-induced CKD in mice and in rats with progressive CKD due to polycystic kidney disease, high PTH is associated with cortical porosity development, Interestingly, the PTH response to CKD also differs due to the genetic strain of mice and these changes correlate with porosity development." (PMID 38505524, 2024).
Primary hyperaldosteronism (5 papers, 2014 to 2024). A form of hyperaldosteronism caused by a defect within the adrenal gland. "Furthermore, PTH levels are higher in patients with primary hyperaldosteronism." (PMID 25254042, 2014). "Spironolactone administration and surgical ablation of adenoma in Primary Hyperaldosteronism patients both brought PTH and calcium serum levels towards the normal range (while not necessarily inside the normal range)." (PMID 38785509, 2024).
renal cell carcinoma (5 papers, 2021 to 2026). "However, the diagnosis of PTHrP‐producing renal cell carcinoma is strongly supported by the markedly elevated serum PTHrP level with suppressed intact parathyroid hormone, together with its rapid normalization immediately after nephrectomy." (PMID 41567516, 2026). "The chief cells of CBT are frequently positive for chromogranin and Syn and negative for epithelial membrane antigen, parathyroid hormone, pancytokeratin, thyroid transcription factor, HMB-45, and renal cell carcinoma marker." (PMID 36086729, 2022).
sleep disorder (5 papers, 2013 to 2024). A change from the patient's baseline sleeping pattern, in the hours slept and/or an alteration/dysfunction in the stages of sleep. "Some models also incorporate reversible predictors such as C-reactive protein, albumin, calcium, and parathyroid hormone to forecast the risk of sleep disorders." (PMID 39408273, 2024). "In severe kidney hyperparathyroidism, PTH may play a causative role for sleep disorders and parathyroidectomy could improve the sleep quality in half of the HD cases." (PMID 34604382, 2021). "Our study demonstrated a significant association between sleep disorders and serum levels of vitamin D in HD patients, even after adjusting confounding factors such as Ca, P, and PTH level, which is parallel to the results of prior researches in patients with SLE and elderly adults." (PMID 34604382, 2021).
Tetany (5 papers, 2015 to 2026). A condition characterized by intermittent involuntary contraction of muscles (spasms) related to hypocalcemia or occasionally magnesium deficiency. "Although there was a slight decrease in calcium levels to 8.1 mg/dL, the PTH level remained normal, and no tetany was observed." (PMID 39262524, 2024). "Follow-up blood tests showed normal levels of PTH and calcium without any signs of tetany, leading to the discontinuation of calcium lactate and alfacalcidol." (PMID 39262524, 2024). "One year after the COVID-19 infection, the patient showed no signs of tetany and maintained normal calcium and PTH levels without medication." (PMID 39262524, 2024).
venous thromboembolism (5 papers, 2014 to 2023). Occlusion of the lumen of a vein by a thrombus that has migrated from a distal site via the blood stream. "Furthermore, among 27,685 subjects (25–87 years) participating in Tromsø 4 (1994–1995) and 8547 individuals participating in Tromsø 5 (2001–2002) surveys, where total calcium and PTH were measured, 712 cases of venous thromboembolism (VTE) were documented during a median follow-up of 15 years." (PMID 37997987, 2023).
Abdominal obesity (4 papers, 2012 to 2024). Excessive fat around the stomach and abdomen. "Twelve weeks of increased whey protein intake in subjects with abdominal obesity did not affect markers of bone turnover significantly, although tended to increase PTH levels." (PMID 35422766, 2022). "Information on abdominal obesity was not available in the HOST Study, but we were able to adjust for BMI, plasma PTH and 1,25(OH)2D levels and show an association between vitamin D and MetS in CKD patients independent of these important confounders." (PMID 22784560, 2012).